IFNG (interferon gamma)
Diseases named in the same sentence as IFNG in open-access papers (continued):
Sharing a sentence is not in itself a finding about the gene and the disease.
infection (continued). "This led to a faster and stronger local CD4 T cell response post infection, consisting of multifunctional IFNγ/TNFα-producing Th1 T cells and IFNγ/TNFα/IL-17-producing Th17 T cells, and a faster recruitment of innate immune cells." (PMID 34925371, 2021). "To define which pathway was required for XWK4-activated inflammasome activation, we analyzed caspase-1 activation in Ifnar–/– and Ifnar–/–Ifnγ–/– double knockout (AG6) BMDMs in response to XWK4 infection." (PMID 34869331, 2021). "A total of 11,984 genes were differentially expressed during the late stage of the infection, most notably interferon-gamma, interleukin-6, and immunoglobulin transcripts." (PMID 34578212, 2021). "Gidwani K, Jones S, Kumar R, Boelaert M, Sundar S. Interferon-gamma release assay (modified QuantiFERON) as a potential marker of infection for Leishmania donovani, a proof of concept study." (PMID 34292942, 2021). "Stimulating BMDMs with IFNγ prior to infection prevented Mtb-induced expression of Fasn and Scd2, suggesting that IFNγ limits de novo synthesis of SFAs and MUFAs by infected macrophages." (PMID 34951591, 2021). "IFNγ is the major mediator produced during some of these infections that promotes alterations in BM cells, via the expansion of LSK (Lineage- Sca1+ cKit+) cells and the increased differentiation of cells from the myeloid lineage." (PMID 34987496, 2021). "At 14 h after infection, unstimulated, IL-4- or IFNγ-treated NRAMPG169 C57BL/6N BMDM showed significantly higher nitrite levels compared to C57BL/6N BMDM." (PMID 34359992, 2021). "WT and Il15ra-/- mice received neutralizing anti-IFNγ antibody 18 hours before infection and at 1 dpi and were sacrificed at 3 dpi." (PMID 34956227, 2021). "There is also a close temporal correlation between T cell IFNγ responses and rapid protection that is induced by a C-strain vaccine five, three, or one day prior to challenge infection." (PMID 33671399, 2021). "Addition of IFNγ 1 h after establishment of infection still resulted in a dampening of the epithelial release of IL-8, but not IL-6." (PMID 34015044, 2021). "Altogether, these data show that the TH1 cells are the predominant CD4 T-cell subset produced during persistent UgCl223 infection, but IFNγ production by these TH1 cells is impaired." (PMID 35186781, 2021). "Heightened IFNγ expression by NK cells at 3.5 days post-infection was coincident with elevated NK cell proliferation at this time point in MCMV-Δm15 infected mice." (PMID 34358016, 2021). "Independent of the role of hepcidin, several other cytokines such as tumor necrosis factor alpha, interferon gamma, interleukin-1, and interleukin-6 also modulate iron metabolism and the iron-withholding defense during infection." (PMID 34247585, 2021). "Either way, expression of Tbet in naïve B cells is commonly induced by IFNγ through a feed forward mechanism and IFNγ plasma levels are also correlated positively with the increase in aMBCs early in infection." (PMID 34684226, 2021). "Of note, in all cases, Ct values for IFNγ were >33, indicating low total levels of this transcript throughout infection." (PMID 34205098, 2021). "IFNγ is another critical cytokine for host defense against B. pseudomallei in mouse models of infection and in vitro." (PMID 33571211, 2021). "A comparison of the TEM images of C. trachomatis-infected and infected+IFNG-treated HL-60 cells showed similar chlamydial forms at 48 h post-infection." (PMID 34819931, 2021). "CXCL9 enables migration of more circulating TM cells to sites of infection, enhancing the activation of local DCs and NK cells and the establishment of an IFNγ-driven antiviral state providing broad protective immunity against unrelated microbial pathogens." (PMID 34516896, 2021). "This reduced recruitment of APCs to the sites of infection not only delays IFNγ induced T cell priming, but also leads to a delayed initiation of the adaptive immune response as fewer APCs are able to present parasite specific antigens." (PMID 33968021, 2021).
infection (continued). "On the other hand, the resistant group displayed a decrease in the involvement of both IFNγ and IL-10 in the network after infection diagnosis." (PMID 33617528, 2021). "The majority of SARS-CoV-2-specific T-cells show an effector phenotype with the dominant production of antiviral proteins, such as interferon-gamma, to terminate infection." (PMID 34202697, 2021). "Cytokine ELISA results further confirmed that, at 48 h after infection, the secretion of IFNg and TNFα in T2KO and DKO BALF was significantly reduced as compared with WT and TKO mice." (PMID 34939151, 2021). "But the decrease in the percentage of CLP upon infection with strain 25291 is dependent on the activation of Mφ by IFNγ, since MIIG mice have the same percentage of CLP as uninfected mice." (PMID 34987496, 2021). "Increased GC, IFNγ, TNF and NO levels have been associated with augmented thymocyte apoptosis during infection and other conditions." (PMID 34987496, 2021). "Three key proteins generally involved in infection and inflammation (IL6 IL18, and IFNG) are the focus of this analysis and are associated with 10 other proteins." (PMID 35145507, 2021). "After STM infection populations of lymph-migratory ILCs display increased expression of RORyt+ and display elevated levels of IFNγ." (PMID 33414524, 2021). "Consistent with a chronic inflammatory state, the serum levels of pro-inflammatory cytokines such as TNFα, IFNγ, and IL-1β increased as a result of the infection in the WT and FPR2-/- mice, although the IL-1β increase in the FPR2-/- mice was not significant." (PMID 34784372, 2021). "2-4 weeks post infection with 40 cercariae, S. mansoni antigen stimulated splenocytes show increased expression of IFNγ, as well as the Th2 cytokines IL-5 and IL-4, when compared to uninfected controls." (PMID 33953712, 2021). "Fth1−/− mice had lower levels of circulating tumor necrosis factor (TNF)-alpha, interferon-gamma (IFN-gamma) and interleukin (IL)-6 than Fth1+/+ mice, 60 days after infection." (PMID 35008695, 2021). "We have not directly measured arginase in BM iMO in this study, but iNOS production was clearly elevated throughout the course of infection through a IFNγ-dependent pathway, most likely involving STAT1 signaling." (PMID 34557190, 2021). "IL-1β, IL-6, IL-8, MCP-1 and IFNγ, were previously reported to be elevated in lethal infection using a high dose of B. pseudomallei 1026b in AGMs." (PMID 33571211, 2021). "In summary, IFNγ/IL10 inversely correlates with the immunological load of infection in an in vitro system, in septic mice and when comparing bacteremic and non-bacteremic critically ill patients." (PMID 33767693, 2021). "The infection induced increased intestinal IFNγ and BMP2 production during the acute phase as well as an increase in the inflammatory infiltrate." (PMID 33561140, 2021). "IFNγ is clinically used against infection in patients with Chronic Granulomatous Disease, although it is also effective against Mycobacterium tuberculosis, Salmonella and fungal infection." (PMID 34248997, 2021). "The time course RT-qPCR analysis demonstrated a dramatic increase in the expression of the proinflammatory cytokine mRNAs for CXCL-13, IFNγ, and IL-6 with infection." (PMID 34451461, 2021). "Infection increases the proportions of RORyt+ T-bet+ ILCs, levels of IFNγ, and IFNγ/GM-CSF co-expression." (PMID 33414524, 2021). "Interferon-gamma release assays (IGRAs) are immunoassays based on the measure of the production of IFN-γ produced after T cell ex vivo stimulation by M. tuberculosis-specific antigens also used to assess for a previous exposure or infection to M. tuberculosis." (PMID 35003135, 2021). "During 45–60 min post infection, the fold change in iNOS and IFNγ have been increased together with high nitrite production resulting in significant decrease in parasite load in transfected system (CTI and CTIM)." (PMID 35011356, 2021).
infection (continued). "The infection of spheroids with SFV/IFNg prevented the migration or distribution of 4T1/eGFP cells within the well." (PMID 34835178, 2021). "And in fact, brain tissue of chronically infected TKO mice showed increased TNF and IFNγ as well as increased production of these cytokines released by CD4+ T cells in the chronic phase of infection." (PMID 33968021, 2021). "This increased weight loss correlated with worsened survival, as 11 of 12 mice treated with the IFNγ-neutralizing antibody succumbed to the infection versus only 2 of 12 mice treated with the isotype-control (p = 0.0004)." (PMID 33572859, 2021). "With respect to the four main thymocyte populations, DP, CD4 single positive (SP) and CD8SP are the ones most affected after infection, in an IFNγ and NO independent manner." (PMID 34987496, 2021). "IFNγ expression serves as a reassuring control of previously known infection-induced brain changes, results demonstrate low IFNγ at 14dpi consistent with lower numbers of T cells at this early stage in the brain (left)." (PMID 33816350, 2021). "The capacity of the inflammatory cascade, and specifically of interferon gamma (IFN-γ), to curtail the infection in immunocompetent individuals is in great part through starvation of T. gondii of tryptophan (TRP)." (PMID 34177652, 2021). "Specifically, infection with Toxoplasma gondii led to the secretion of interferon-γ (IFNγ) by NK cells and this cytokine was responsible for monocyte priming and the development of regulatory capacity." (PMID 34557190, 2021). "Interferon-γ (IFN-γ, encoded by IFNG) and its receptor (encoded by IFNGR1) exert vital effects on the inflammatory response against pathogen infection." (PMID 34646402, 2021). "During infection in Merino sheep, the Th2 polarisation occurs around 9 days post-infection in the hepatic lymph nodes and 18 days post-infection in the liver, with a significant increase in IL-4 expression that suppresses IFNγ levels." (PMID 34207215, 2021). "In human leprosy, intradermal IFNγ administration has been shown to change local infection from lepromatous to tuberculoid leprosy, with increases in the numbers of CD4+ T-cells and reductions in bacterial numbers in dermal biopsies." (PMID 34684248, 2021). "Ongoing research will be needed to evaluate the effect of the early-phase IFNγ response shown here on long-term infection outcomes." (PMID 34015044, 2021). "The severity of disease was lower in healthy volunteers who exhibited increased IFNγ production by peripheral blood mononuclear cells stimulated with heat-killed C. jejuni before experimental infection." (PMID 34938670, 2021). "While IFNγ increased in the BALF of both strains of mice at day 27 post infection, it tended to be at higher levels in the IL-4Rα−/− neonates." (PMID 34682248, 2021). "Shown are the frequencies of nucleocapsid-specific CD4+ (left) and CD8+ (right) T cells, as measured by IFNγ production upon stimulation with ancestral nucleocapsid peptides, in infection-naïve (top) and convalescent (bottom) individuals." (PMID 34636722, 2021). "In contrast, cytokines related to a Th1-immune response [IL-2, IL-12(p70), and IFNγ] were significantly elevated in immunized mice, while these cytokines remained almost unchanged in control mice in response to an infection." (PMID 33514747, 2021). "Here, deletion of the IFNγR1 subunit had a substantially more profound impact on the acute infection of RMT/MT P. chabaudi infections, than was observed in SBP infections, showing that an early IFNγ response is important in attenuating parasitaemia." (PMID 34532703, 2021). "Surprisingly, significant reduction in the level of antibodies was observed in the protected mice, and levels of cytokines including IFNγ, IL-2, IL-8, IL-10, and IL-12, and of nitric oxide after infection with B. rodhaini also diminished." (PMID 34414129, 2021).
infection (continued). "To model the proposed in vivo kinetics more closely, we allowed time for the epithelial infection to establish itself within the microfluidic system prior to the addition of IFNγ." (PMID 34015044, 2021). "In particular, memory CD8 T cells and induction of IFNγ are primarily responsible for protection against lethal secondary infections with the widely studied type I RH strain, which has a lethal dose of one parasite in naïve mice." (PMID 34871323, 2021). "The RV144 vaccine regimen strongly induced the IFNγ pathway, more specifically the activation of IRF7, which was associated with reduced risk of acquisition of infection." (PMID 34806296, 2021). "This suggests that RMT infections induce a greater macrophage, and IFNγ-dependent response, compared with SBP infections." (PMID 34532703, 2021). "Levels of IFNγ+ T-cells at three months after vaccination were comparable with those at three, six, and twelve months after infection." (PMID 34960185, 2021). "Th1-type cytokines, notably IFNγ stimulation, provides resistance to infection and ability to kill the intracellular bacteria to the stimulated macrophages (including alveolar macrophages)." (PMID 34946140, 2021). "In contrast, A/E pathogens that lack Stx, like Citrobacter rodentium and EPEC, activate expression of IFNγ during infection." (PMID 33529199, 2021). "The three strains were used to infect naive and interferon gamma (IFN-γ) preactivated murine bone marrow-derived macrophages (BMDMs) at a multiplicity of infection (MOI) of 0.1:1 (bacteria/macrophages)." (PMID 34549992, 2021). "This is usually the case with bovine TB when following infection, the immune response is influenced by T-cells that direct and maintain a response dominated by IFNγ release." (PMID 33848298, 2021). "Our results showed that infection with T. cruzi triggers a robust inflammatory response in the acute phase, with the production of inflammatory cytokines, such as IFNγ and TNFα, which have been shown to activate macrophages to eliminate the parasite." (PMID 34784372, 2021). "IFNγ secreted at early stages of infection enhances antigen presentation by antigen-presenting cells (APCs), such as macrophages and dendritic cells, by inducing MHC expression." (PMID 34938670, 2021). "Polarisation to classically activated macrophages, or M1 macrophages, occurs in response to infection or injury, and can be induced by exposure to microbial by-products such as lipopolysaccharide (LPS) or by cytokines interferon gamma (IFNG) and TNFA." (PMID 34771552, 2021). "Similar to the multivariate correlates identified at day 28, the Vi IgA levels measured at days 118 and 208 were elevated in protected participants, whereas ADNKA IFNγ release was a predictor of infection." (PMID 33180929, 2021). "Further, this independence is maintained even when the mice are treated with an anti-IFNγ antibody during infection to create a strongly polarised Th2 environment." (PMID 34329367, 2021). "Animals who underwent full splenectomy prior to infection however demonstrated significantly lower serum IFNγ, as well as increased bacterial dissemination." (PMID 34015044, 2021). "By contrast, the levels of NF-κB-mediated IL-2, IFNγ, and perforin, which are primarily produced by T lymphocytes and NK cells, increased significantly during infection, suggesting the establishment of a certain response of these immunocompetent cells." (PMID 34785771, 2021). "IDO is an inducible enzyme, and while IDO induction by infection alone can be observed, IFNG is a potent inducer of its expression and activity." (PMID 34819931, 2021). "The cytokine interferon gamma (IFNγ) is induced during infection and is critical for restricting T. gondii growth in human cells." (PMID 34871166, 2021). "Clinical studies suggest that IFNγ, a cytokine associated with immune responses mediated by TH1 cells, is beneficial and can be protective against infection." (PMID 35186781, 2021).
infection (continued). "Interferon gamma (IFNγ) has been known since the 1980s to be expressed during T. gondii infection and to be critical for restricting infection in mice." (PMID 34871166, 2021). "The IFNγ content of the ΔhtpG infection group was significantly lower than that of the WT and CΔhtpG infection group (p < 0.01 and p < 0.05, respectively)." (PMID 34869065, 2021). "Rather, the levels of IFNγ+ T-cells, which are reportedly lower in patients with severe than mild infection, are presented to put the surprisingly low IFNγ+ T-cell responses from three months into context." (PMID 34960185, 2021). "Our data demonstrates a further seemingly anti-inflammatory role for splenic IFNγ in modulating IL-8 expression in kidney epithelial cells following infection." (PMID 34015044, 2021). "These cells are recruited to the site of infection and are capable of producing various cytokines, including interferon gamma (IFN-γ) and tumor necrosis factor alpha (TNF-α)." (PMID 34604367, 2021). "TNF-α has been shown to be a component of killing/control during O. tsutsugamushi infections, and during infection with other intracellular pathogens, either alone or synergistically with IFNγ or IL2." (PMID 34287349, 2021). "In longitudinal studies, we and others have previously shown significant decreases in the IFNγ response up to twelve months after infection." (PMID 34960185, 2021). "Levels of cytokine-producing T-cells were remarkably stable between three and twelve months after infection, and were comparable to IFNγ+ and IFNγ+IL-2+ T-cell responses but lower than IL-2+ T-cell responses at three months after vaccination." (PMID 34960185, 2021). "We observed that IRF1 and IFNγ both strongly induced the expression of RARRES3 which led us to question if infection restriction by IRF1 was due to the induction of RARRES3 expression." (PMID 34871166, 2021). "We observed that the infected cells transfected with the synthetic circuit showed higher expression of pro-inflammatory cytokines such as iNOS and IFNγ with 2–7 fold change as compared to the infection group." (PMID 35011356, 2021). "As the principal regulator of HSCs both during homeostasis and under infection stress, IFNγ can strongly promote HSCs proliferation and increase the proportion of Sca‐1‐positive cells in WT and Irf8−/− LKs ex vivo." (PMID 34365741, 2021). "Infection with active TB promotes accumulation of inflammatory cytokines, including interleukin-17 (IL-17) and interferon gamma (IFNγ), which trigger necrosis, resulting in the cavitation of the infected area, in the lungs." (PMID 34441287, 2021). "CD4+ T cells differentiate into TH1 cells that produce IFNγ and TNFα in the infection with rickettsiae and orientiae." (PMID 34452021, 2021). "In DENV-4, IL-2 (p<0.05), IL-8 (p<0.01), IL-12 (p<0.01), and IFNγ (p<0.001) were significantly upregulated in primary than secondary infection, while GM-CSF (p<0.0001) and IP-10 (p<0.001) were significantly upregulated in secondary infection." (PMID 34447698, 2021). "IFNγ production by NK cells was slightly higher in MCMV-Δm15 infected mice compared to MCMV-Rev infected mice at day 1.5 post-infection." (PMID 34358016, 2021). "People with symptomatic infections had significantly higher IFNγ-producing T cell responses at six months after infection compared to people with asymptomatic infection." (PMID 34578848, 2021). "Following clearance of infection, macrophages produced proteins involved in interferon-gamma signaling, phagocytosis and hemostasis." (PMID 34141493, 2021). "We found that ablation of RARRES3 expression partially prevented the IFNγ and infection-dependent cell death phenotype in HFF cells." (PMID 34871166, 2021). "Of further interest, murine studies using IFNγ or IFNγ receptor knockouts and Spn infection have shown reduced lung CFUs over wild-type controls with no change in the level of morbidity." (PMID 33705390, 2021).